TLR5 (toll like receptor 5)
Diseases named in the same sentence as TLR5 in open-access papers (continued):
Sharing a sentence is not in itself a finding about the gene and the disease.
non-small cell lung carcinoma (4 papers, 2015 to 2025). A group of at least three distinct histological types of lung cancer, including non-small cell squamous cell carcinoma, adenocarcinoma, and large cell carcinoma. "In our previous study, we found that the expression of TLR5 was remarkably higher in non-small cell lung cancer (NSCLC) tissues than that in normal tissues, but the activation of TLR5 signaling pathway in NSCLC was still unknown." (PMID 25603867, 2015). "TLR4, TLR5, TLR7, and TLR8 were more highly expressed in non-small cell lung cancer (NSCLC)." (PMID 41471188, 2025).
oral carcinoma (4 papers, 2014 to 2024). "They further found that TLR5 expression levels were also greater in oral cancers than in skin cancers and concluded that TLR5 is usually activated more endogenously in oral cancers." (PMID 38685971, 2024). "Polymorphisms in TLR7 and TLR5 were recently associated with oral cancer suppression, while polymorphisms in TLR4 and TLR2 were associated with oral cancer progression." (PMID 38850110, 2024). "The significance of TLR5 in oral carcinoma has been demonstrated by assessing TLR5 expression in a cohort of 119 patients with oral tongue squamous cell carcinoma." (PMID 24932259, 2014).
ovarian carcinoma (4 papers, 2017 to 2024). A malignant neoplasm originating from the surface ovarian epithelium. "Despite similar cancer sizes, TLR5-responsive mice exhibited significantly higher serum IL-6 levels, and ovarian cancer progressed more rapidly than in the TLR5-dificient mice." (PMID 38541242, 2024). "Abnormal TLR5 functioning is related to the onset of gastric, cervical, endometrial and ovarian cancers." (PMID 28404962, 2017).
Parkinson disease (4 papers, 2015 to 2025). A progressive degenerative disorder of the central nervous system characterized by loss of dopamine producing neurons in the substantia nigra and the presence of Lewy bodies in the substantia nigra and locus coeruleus. "Consistent reports of increased TLR5 expression exist in the context of further neurodegenerative disorders, such as Parkinson’s disease and dementia with Lewy bodies." (PMID 32912327, 2020). "More importantly, expression levels for TLR2, TLR5, and CD14 are increased in Parkinson’s disease." (PMID 25586882, 2015).
pneumococcal infection (4 papers, 2013 to 2024). Infections with bacteria of the species streptococcus pneumoniae. "Our results prove the molecular mechanism of well-maintained TLR5 expression and signaling via caveolin-1 upregulation in old macrophages and provide a new model for developing a vaccine adjuvant against pneumococcal infection in the elderly." (PMID 26223660, 2015). "To elucidate the role of FlaB-dependent TLR5 in aged mice, we designed a vaccine model against pneumococcal infection." (PMID 26223660, 2015). "It was hypothesized by the authors that activation of Tlr5 signaling might possibly enhance alternate innate immune defenses against the pneumococcal infection." (PMID 24992587, 2014).
skin cancer (4 papers, 2015 to 2026). "We conclude that TLR-5-mediated signalling is involved in tumour initiation in two different skin cancer models." (PMID 25575023, 2015). "Both of the mouse models in which we demonstrated a role for leukocytic TLR-5 sensing in wound-induced skin cancer are characterized by chronic inflammation." (PMID 25575023, 2015). "We conclude that HMGB1 is upregulated in wound-associated mouse and human skin tumours and that HMGB1 levels are regulated by leukocytic TLR-5 signalling." (PMID 25575023, 2015). "We have found a previously unknown role for Toll-like receptor (TLR)-5, the receptor for bacterial flagellin, in skin tumour formation, both in the InvEE mouse model and in wild-type (WT) mice treated with chemical carcinogens." (PMID 25575023, 2015).
urinary tract infection (4 papers, 2017 to 2021). "The non-synonymous SNP rs5744174 (Phe616Leu) in the TLR5 ectodomain, which abrogates flagellin-induced signaling, has been associated with urinary tract infections and hepatitis B infection, but it never been studied in the context of A. fumigatus infection." (PMID 33510868, 2021).
allergic rhinitis (3 papers, 2017 to 2021). Inflammation of the nasal mucous membranes caused by an IgE-mediated response to external allergens. "Similarly, stimulation of TLR5 on DCs by bacterial flagellin induces Th2 responses that have been associated with the prevalence of allergic rhinitis, although, similarly to other TLR ligands, high doses can induce tolerogenic responses." (PMID 33803079, 2021).
ankylosing spondylitis (3 papers, 2015 to 2024). An autoimmune chronic inflammatory disorder characterized by inflammation in the vertebral joints of the spine and sacroiliac joints. "In another study, it was reported that infliximab decreased the expression of TLR-4 and TLR-5, the study indicated that higher TLR-4 and TLR-5 expression exacerbated inflammatory conditions in ankylosing spondylitis." (PMID 38521924, 2024). "Another study reported that anti-TNF treatment decreases TLR5 (and TLR4) expression among ankylosing spondylitis patients, which supports the hypothesis of TLR5 having a role in the differential anti-TNF response." (PMID 26440629, 2015).
aspergillosis (3 papers, 2016 to 2021). Aspergillosis is an infection, growth, or allergic response caused by the Aspergillus fungus. "However, a mutation in TLR5 leading to a stop codon was identified as a risk factor for aspergillosis." (PMID 29326692, 2017). "Other SNPs in the TLR5 coding region have been associated with an increased risk of aspergillosis, for example, insertion of a STOP codon (Arg392Ter; rs5744168) increased the risk of aspergillosis in HSCT patients." (PMID 33510868, 2021). "In aspergillosis, we found that NLRC4 activation occurs through the TLR5/NAIP5/NF-κB-dependent pathway." (PMID 26972847, 2016).
co-infection (3 papers, 2017 to 2021). "As this pathway is not affected by IAV and to address the gap in the research using human models, we examined TLR5 agonism in a simulated co-infection with IAV and S. pneumoniae in human monocytes." (PMID 34644311, 2021). "Other studies using mouse models demonstrated that TLR5 agonism improved the efficacy of antibiotics in the treatment of IAV/S. pneumoniae co-infections." (PMID 34644311, 2021). "Densitometric analysis of the western blots (n = 3) indicated that transfection of HBE cells with either of the two TLR5 siRNA duplexes significantly attenuated HBD-2 protein induction in response to co-infection with HRV and PA." (PMID 28489911, 2017). "Since flagellin is a known ligand for the extracellular receptor TLR5, we examined whether TLR5 knockdown would impact HBD-2 protein production following co-infection with HRV and PA." (PMID 28489911, 2017). "A TLR5 agonist has previously been shown to improve the efficacy of antibiotics in the treatment of IAV and S. pneumoniae co-infections in mice." (PMID 34644311, 2021). "Most TLR mRNAs, including TLR4, TLR5, and TLR8 were upregulated in the severe group, consistent with viral and bacterial co‐infection that was common among severe cases." (PMID 33135345, 2020). "Taken together, these data indicate that bacterial flagellin, acting via TLR5, plays a role in mediating the observed synergistic increase in HBD-2 production following HRV and PA co-infection." (PMID 28489911, 2017). "In addition, previous work in mouse models have established that a TLR5 agonist can have beneficial therapeutic effects when combined with antibiotic administration in the treatment of IAV and S. pneumoniae co-infections." (PMID 34644311, 2021). "Additionally TLR5 agonism has improved the efficacy of antibiotics in treating IAV and S. pneumoniae co-infections in mice." (PMID 34644311, 2021). "Due to the encouraging results using TLR5 agonism as a treatment in mice, we sought to investigate what effect TLR5 agonism may have on immune responses S. pneumoniae and IAV co-infection by human monocytes." (PMID 34644311, 2021).
dysplasia (3 papers, 2014 to 2022). A usually neoplastic transformation of the cell, associated with altered architectural tissue patterns. "Overall, lower TLR5 expression was observed in metaplasia samples when compared to low-grade dysplasia samples." (PMID 35614270, 2022). "Although TLR5 expression, the potential for activation by a dysbiotic flagellated microbiota, and correlation with dysplasia have been elucidated, more studies are needed to identify the direct interactions between dysbiotic microbiota and TLR5." (PMID 34439930, 2021). "Also TLR5, a receptor recognizing bacterial flagellin and activating immunity reaction, is overexpressed in metaplasia-dysplasia-carcinoma sequence, showed higher expression in LGD when compared non-dysplastic Barrett’s esophagus, but seems not to be a potential marker for progression." (PMID 35614270, 2022).
esophageal adenocarcinoma (3 papers, 2020 to 2022). A malignant tumor with glandular differentiation arising predominantly from Barrett mucosa in the lower third of the esophagus. "A variety of TLRs such as TLR3 and TLR5 have been shown to be overexpressed in esophageal squamous cell carcinoma and esophageal adenocarcinoma." (PMID 34795689, 2021). "All in all, the data suggest that TLR5 and NF-κB are involved in the pathogenesis and dissemination of esophageal adenocarcinoma." (PMID 32023907, 2020).
Hepatic steatosis (3 papers, 2015 to 2022). Steatosis is a term used to denote lipid accumulation within hepatocytes. "After 12 weeks of HFD feeding, the TLR5−/− mice gained more weight and showed significantly higher glucose intolerance and hepatic steatosis than C57BL/6 mice." (PMID 26681840, 2015). "While the exact role of TLR5 in NAFLD remains unknown, two separate studies have shown that knock-down of TLR5 accelerates hepatic steatosis, susceptibility to liver injury and NASH, thereby assigning it a more protective rather than harmful role." (PMID 33193105, 2020). "In conclusion, with the exception of TLR5, hepatic TLRs, upon binding by gut bacteria-derived products, set into motion a cascade of inflammatory and fibrotic signals, thereby abetting the progression of fatty liver to NASH." (PMID 33193105, 2020).
lymph node metastasis (3 papers, 2017 to 2024). "TLR5 overexpression correlated negatively with histological grade and positively with lymph node metastasis." (PMID 29179462, 2017). "We found that TLR5 overexpression correlated significantly with lymph node metastasis and tumor grade (p<0.01)." (PMID 29179462, 2017). "Of the 95 lymph node metastases, analyzable samples were available for 70 (TLR1), 72 (TLR2), 77 (TLR4), 58 (TLR5), 76 (TLR6), 72 (TLR7), 76 (TLR8) and 70 (TLR9) cases." (PMID 38709790, 2024). "SB-NETs and their lymph node metastases express cytoplasmic TLR 1–2 and 4–9 and nucleic TLR5." (PMID 38709790, 2024).
periodontitis (3 papers, 2019 to 2025). An acute or chronic inflammatory process that affects the tissues that surround and support the teeth. "Comparison of healthy and periodontitis tissues showed that periodontitis was characterized by loss of TLR1, TLR2, and TLR5 expression in the superficial epithelial cell layers." (PMID 31448244, 2019).
pyelonephritis (3 papers, 2009 to 2019). An inflammatory process affecting the kidney. "Specific genes suggested to mediate host resistance to kidney infections include those encoding Toll-like receptor 5 (Tlr5) and the antimicrobial peptide cathelicidin." (PMID 23055930, 2012). "Although previous studies in mice indicate that TLR4, TLR5, and TLR11 regulate susceptibility to cystitis and pyelonephritis, the role of TLRs in human UTI pathogenesis is poorly understood." (PMID 19543401, 2009). "Flagellin also activates renal collecting duct cells via TLR5, which enables upregulation of CXCL1 and CXCL2 to provide renal host defense against pyelonephritis." (PMID 31776239, 2019). "In order to discover novel polymorphisms associated with UTIs, we PCR-amplified and sequenced the coding regions of 7 TLR pathway genes (TLR2, TLR4, TLR5, MYD88, TIRAP, TRIF, and TRAM) in subjects with a high frequency of cystitis or pyelonephritis episodes." (PMID 19543401, 2009).
respiratory infection (3 papers, 2014 to 2022). "Our present results show that Tlr5−/− mice are more susceptible to B. pseudomallei in a model of respiratory infection, in contrast to deficiency in Tlr2, which actually confers resistance, or Tlr4, which has no apparent effect on survival." (PMID 25232720, 2014). "Although MyD88 is an adapter molecule for all three of these TLRs, mice deficient in Myd88 show a similar phenotype to deficiency in Tlr5 after respiratory infection with B. pseudomallei." (PMID 25232720, 2014). "Mice lacking TLR5 are susceptible to the gram-negative bacterium Salmonella typhimurium, a common pathogen causing the acute food-borne gastroenteritis, and Pseudomonas aeruginosa, the most common pathogen causing hospitalized respiratory infection." (PMID 35073369, 2022).
schizophrenia (3 papers, 2017 to 2021). A major psychotic disorder characterized by abnormalities in the perception or expression of reality. "Increased levels of TLR4 and TLR5 monocytes and TLR5 T reg/Tact cells have been exhibited in drug-naïve schizophrenia patients compared to controls, correlating with cognitive deficits severity." (PMID 34299291, 2021). "Results revealed increased TLR4/TLR5 and decreased ErbB4 expression in schizophrenia relative to the control subjects." (PMID 28646138, 2017). "Although TLR5 was also up-regulated in schizophrenia, the stimulation of this receptor resulted in a pro-inflammatory cytokine response comparable to that measured in control subjects." (PMID 28646138, 2017). "Recently, we demonstrated up-regulated TLR4 and TLR5 on monocytes and lymphocytes of drug-naïve schizophrenia patients; TLR4, but not TLR5, alterations were normalized by antipsychotic treatment." (PMID 28646138, 2017).
Stroke (3 papers, 2020 to 2024). Sudden impairment of blood flow to a part of the brain due to occlusion or rupture of an artery to the brain. "First, we found several metabolic pathways shared in two diseases and BEX2 is negatively associated with glycolysis in both stroke and MS, while TLR5 and P4HA1 are positively associated with glycolysis in stroke and MS." (PMID 39021802, 2024). "TLR5 and P4HA1 are positively associated with glycolysis in both diseases; while BEX2 is negatively associated with glycolysis in both stroke and MS." (PMID 39021802, 2024).
tongue cancer (3 papers, 2014 to 2023). A malignant neoplasm affecting the tongue. "TLR5 expression was more pronounced in tongue cancer cells than in adjacent apparently normal epithelium and high expression levels of TLR5 predicted a poorer prognosis." (PMID 25309546, 2014). "The pathogen recognition receptor toll-like receptor 5 has been reported to play an important role in the pathophysiology of tongue carcinoma and might represent a link between bacterial infection and cancer." (PMID 26176534, 2015).
vasculitis (3 papers, 2014 to 2025). "TLR5 is a key pattern recognition receptor of the innate immune system whose activation can trigger potent proinflammatory cascades implicated in other forms of vasculitis." (PMID 41307202, 2025). "In that same study, both TLR4 and TLR5 were found to be differentially expressed spatially within the arterial wall, stimulating different types of immune activation and vasculitis when stimulated with either LPS (a TLR4 agonist) or flagellin (a TLR5 agonist)." (PMID 26998496, 2016).
Arthritis (2 papers, 2017 to 2018). Inflammation of a joint. "The expression of miR-150, which was increased in the three models of intestinal inflammation (IL10−/−, DSS, and TLR5−/−), was unaltered in the arthritis model, as were the remaining miRNAs of the signature." (PMID 28566745, 2017).
astrocytoma (2 papers, 2018 to 2023). "This study aims to analyze the expression levels of plasmatic cell membrane TLRs (TLR1, TLR2, TLR4, TLR5, and TLR6) in human astrocytomas the most prevalent tumors of CNS different grades (II-IV)." (PMID 29912993, 2018). "TLR1, TLR2, TLR4, TLR5, and TLR6 are involved in a diversity of cellular responses, ranging from cell proliferation to cell death, and as such they are the targets of the current study in astrocytomas." (PMID 29912993, 2018). "In this regard, experimental evidence on the increased cell surface expression of TLR1, TLR2, TLR4, TLR5, and TLR6 in astrocytoma samples compared to non-neoplastic brain tissues clearly revealed the involvement of these TLRs in the progression of astrocytoma." (PMID 37822929, 2023). "In summary, increased cell membrane TLR1, TLR2, TLR4, TLR5, and TLR6 expressions were demonstrated in astrocytomas compared to non-neoplastic brain tissue, mostly in GBM group, and particularly in the mesenchymal subtype." (PMID 29912993, 2018). "In the present study, higher expression levels of TLR1, TLR2, TLR4, TLR5, and TLR6 were demonstrated in human diffusely infiltrating astrocytomas (grades II to IV) in comparison to non-neoplastic brain tissue." (PMID 29912993, 2018).
bacterial meningitis (2 papers, 2020 to 2025). Inflammation of the membranes surrounding the brain and spinal cord due to a bacterial infection. "Furthermore, TLR5 senses flagellin from Listeria monocytogenes, which represents one of the major pathogens causing bacterial meningitis in humans." (PMID 32912327, 2020). "In a bacterial meningitis model, activation of TLR5 significantly reduced mortality and decreased the number of bacteria in the brain, suggesting that TLR5-activated meningeal macrophages play an important role in neonatal resistance to bacterial meningitis infection." (PMID 41568029, 2025).
bronchiolitis (2 papers, 2018 to 2025). Inflammation of the bronchioles characterized by swelling of the bronchioles and mucus accumulation. "There are 3 main results in this study concerning the TLR5 rs5744174 (C > T) gene polymorphism in bronchiolitis and post‐bronchiolitis outcome." (PMID 30623075, 2018). "However, bronchiolitis caused by some other virus than RSV was significantly more common among children with the variant genotype in the TLR5 rs5744174 gene." (PMID 30623075, 2018). "First, the TLR5 rs5744174 variant genotype was associated with non‐RSV etiology of bronchiolitis." (PMID 30623075, 2018). "No studies are available on the association between TLR5 genes and bronchiolitis caused by other viruses, or between TLR5 genes and the post‐bronchiolitis outcome." (PMID 30623075, 2018). "Thus far, only one study has considered TLR5 genes in respiratory syncytial virus (RSV) bronchiolitis." (PMID 30623075, 2018). "The TLR5 rs5744174 variant genotype may increase the susceptibility to bronchiolitis not caused by RSV." (PMID 30623075, 2018).
bronchopulmonary dysplasia (2 papers, 2018 to 2020). Bronchopulmonary dysplasia is a chronic respiratory disease that results from complications related to lung injury during the treatment of infant acute respiratory distress syndrome in low-birth-weight premature infants or from abnormal lung development in older infants. "The TLR5 (g.1174C>T) variant, which encodes a non-functional protein, is significantly associated with development of severe bronchopulmonary dysplasia in very low-birth weight infants born prematurely." (PMID 29867970, 2018).
Chronic colitis (2 papers, 2015 to 2017). A chronic inflammatory disease of the large intestine (colon, cecum and rectum). "Flagellin-detecting toll like receptor 5 (TLR5) knockout mice colonized with adherent-invasive Escherichia coli (AIEC) during microbiota acquisition drove chronic colitis." (PMID 26617521, 2015).